NRAS (NRAS proto-oncogene, GTPase)
Diseases named in the same sentence as NRAS in open-access papers (continued):
Sharing a sentence is not in itself a finding about the gene and the disease.
tumor (continued). "Tumor samples were analysed using NGS while BEAMing (digital PCR technology combines emulsion PCR with magnetic beads and flow cytometry for the highly sensitive detection and quantification of mutant tumor DNA molecules) has been used to search for KRAS and NRAS mutations in plasma samples." (PMID 30008744, 2018). "In addition, oncogenic NRAS has been mainly studied in respect to cell‐autonomous processes, and tumor–host interactions triggered by the oncogene may have gone under‐appreciated." (PMID 28341702, 2017). "However, the rate of cfDNA mutations in the patients without any prior KRAS/NRAS/BRAF/PIK3CA tumor mutations was 10-fold lower than the cutoff (0.002% ± 0.00014; N = 374)." (PMID 27852040, 2017). "Genomic DNA from primary tumour tissues of 1284 consecutively-collected patients with metastatic colorectal carcinoma (mCRC), originating from different geographical areas within Sardinia island, was screened for somatic mutations in KRAS, NRAS, BRAF, and PIK3CA genes." (PMID 27737711, 2016). "However, despite improved survival for a subset of patients, no benefit is seen for those with KRAS/NRAS mutated tumours." (PMID 27340376, 2016). "Thus, we will treat patients with NRAS mutant tumours as a separate cohort with this combination." (PMID 26410619, 2015). "We electroporated these DCs either without RNA (mock) or with a panel of 16 different RNAs encoding tumor antigens, or parts thereof (MelanA, NRAS, BRAF, GNAQ, GNA11, and WT1), either mutated or not, and either linked to the lysosomal targeting signal DC-LAMP or not." (PMID 26824052, 2015). "By applying the same ‘exclusivity analysis’ to mutation data from other tumor types, however, we identified or confirmed other pairs of mutations—mutant KRAS and BRAF in COAD, mutant EGFR and NF1 in GBM, and mutant BRAF and NRAS in SKCM —that may be synthetically lethal in those tumors." (PMID 26047463, 2015). "That the influence of PTEN expression on prognosis was more pronounced in tumours without BRAF or NRAS mutations is a new observation, and suggests that PTEN loss may be a key biomarker in BRAF-wildtype tumours." (PMID 24830350, 2014). "Tumor size was larger in FNs without NRAS mutations (P < 0.001)." (PMID 25254041, 2014). "Notably, BRAF and NRAS mutations were found to be mutually exclusive (p < 0.001), with no tumor harboring mutations in both genes." (PMID 23673558, 2013). "Tumor tissues from 504 patients with diverse cancers referred to the Clinical Center for Targeted Therapy at MD Anderson Cancer Center starting in October 2008 were analyzed for PIK3CA, RAS (KRAS, NRAS), and BRAF mutations using polymerase chain reaction-based DNA sequencing." (PMID 21829508, 2011). "Cells of various kinds of benign, static neoplasms in vivo show markers of senescence, for example, in melanocytic nevi, which generally carry activating v-raf murine sarcoma viral oncogene homolog B1 (BRAF) or neuroblastoma RAS viral oncogene homolog (NRAS) mutations." (PMID 21418545, 2011). "This analysis focussed on secondary RDT end points: changes in bi-dimensional tumour measurements from baseline after 12 weeks and overall tumour responses (WHO criteria) at week 24, progression-free survival (PFS), safety and biomarkers (BRAF, KRAS and NRAS mutational status)." (PMID 16880785, 2006). "Triple therapy with Remodelin, cetuximab, and 5-Fluorouracil enhanced tumor regression in xenograft mouse models of CRC with wild-type KRAS, NRAS and BRAF." (PMID 39905540, 2025). "Thus, NRAS-BRAF co-mutations are even rarer and may indicate complex tumor heterogeneity." (PMID 40502411, 2025). "Hematoxylin and eosin sections were dissected into multiple, spatially distinct regions within each tumor and directly Sanger sequenced for the relevant region of BRAF and either KRAS or NRAS, as appropriate." (PMID 39751654, 2025).
tumor (continued). "We employed targeted next-generation sequencing to analyze seven actionable driver genes - EGFR, KRAS, NRAS, BRAF, ALK, ROS1, and PIK3CA - in formalin-fixed, paraffin-embedded tumor specimens from Vietnamese NSCLC patients." (PMID 40502411, 2025). "addressed the heterogeneity of the mutations predicting the resistance to anti‐EGFR treatment (KRAS, NRAS, BRAF and/or PIK3CA) in the primary CRC tumours in the context of the proportion of neoplastic cells." (PMID 40302146, 2025). "In preclinical studies, it effectively reduced ERK phosphorylation and inhibited KRAS-mutant tumor growth while sparing HRAS and NRAS." (PMID 41373672, 2025). "BRAF p.Val600Glu mutations were found in three left‐sided and 1 right‐sided tumour, NRAS p.Gln61Lys in 1 right and 1 left‐sided tumour, KRAS p.Lys147Glu and p.Ala146Thr in one left‐sided tumour, and HRAS p.Ala121Thr in the tumour of the rectum." (PMID 40302146, 2025). "We further conducted RNA sequencing analyses to identify novel genes and pathways altered by BAY 11-7082 treatment in context of NRAS, KRAS, and HRAS mutant cancer cells which leads to tumor growth inhibition." (PMID 38982514, 2024). "Using narrow-down analysis, six tumor antigens (AGPS, NRAS, MTDH, PANX1, NOX4, and PPARD) were found to be related to better prognoses as well as the infiltration of antigen-presenting cells in LUAD." (PMID 38331967, 2024). "In agreement with the in vitro findings, the expression of NRAS, p-ERK1/2, CDK4, Cdc25A, and CydlinD1 was inhibited in tumor grafts with the treatment of DHA." (PMID 38778121, 2024). "Tumor staining in SB/AKT/c-Met + TAA and SB/AKT/NRas + TAA was similar to that of saline counterparts, although strong staining was observed within and around the high-grade HCC." (PMID 39254423, 2024). "Considering the interaction between tumor antigens and APCs, these potential antigens were further screened through the TIMER database where it was found that AGPS, NRAS, MTDH, PANX1, NOX4, and PPARD genes were positively correlated with different APCs." (PMID 38331967, 2024). "In summary, all the pathways identified to be downregulated in NRAS, KRAS, and HRAS mutant cancer cell lines upon BAY 11-7082 treatment are prooncogenic and have shown to promote different aspects of tumor growth and progression." (PMID 38982514, 2024). "KRAS, NRAS and BRAF testing on tissue was performed with real-time PCR and revealed a wild-type tumor." (PMID 39064004, 2024). "This was a surprising observation as genetic ablation of mutant NRAS in vivo decreased phosphorylated ERK levels and led to tumor regression." (PMID 39379700, 2024). "The two-tailed Fisher exact test was used to test the null hypothesis that the variable of the mutational state of the KRAS or NRAS gene was independent of the following clinical-histopathological variables: sex, age, tumor location, stage and degree of tumor differentiation." (PMID 39816392, 2024). "Results showed that tumor stage, tumor size, vascular invasion, lymph node metastasis, B-RAF V600E and NRAS Codon 12/13 were significantly different between the two groups." (PMID 37400750, 2023). "A heatmap between normal and tumor tissues showed the expression of G6PD, HRAS, NRAS, TIMM9, and MYCN." (PMID 37143953, 2023). "7/8 (88%) methods found mutually exclusive alterations in KRAS, NRAS or BRAF as a predictive biomarker, from which one, two and four methods proposed this marker in conjunction with tumour sidedness, CMS and across all patients, respectively." (PMID 37666855, 2023).
tumor (continued). "By taking advantage of miR-708 as a powerful tumor suppressor by targeting numerous cancer-initiating or cancer-facilitating genes, we could use miR-708 to combat cancers from multiple aspects in addition to NRAS inhibition, resulting in a net positive outcome." (PMID 37083947, 2023). "The studies with the LLC NRAS KO cells propagated orthotopically in C57BL/6 mice showed that combined MRTX-849 and SHP2 inhibitor, RMC-4550, induced tumor shrinkage, albeit transiently." (PMID 36845684, 2023). "Among all miRNAs with canonical binding sites on the NRAS 3’UTR, we chose miR-708 as our candidate to perform further molecular and functional analysis since miR-708 is a well-known tumor-suppressive miRNA in various cancer types." (PMID 37083947, 2023). "Tumor localization has gained importance with the finding that anti-EGFR therapy combined with chemotherapy is more effective in wild-type KRAS, NRAS, and BRAF patients with left-sided primary CRC tumors." (PMID 37628934, 2023). "By contrast, the rates of tumor growth from orthotopically implanted LLC 46 NRAS KO and LLC 23 NRAS KO cells were markedly reduced relative to parental LLC cells." (PMID 36845684, 2023). "Patients with KRAS, NRAS, PIK3CA and BRAF wild-type tumours were randomised between the pan-HER inhibitor AZD8931 and placebo." (PMID 35256486, 2023). "Currently, an IdyllaTM system for circulating tumor DNA in blood samples have already been developed for BRAF, KRAS, NRAS, and EGFR." (PMID 35474548, 2022). "In addition, we observed that NRAS, MET, and NFE2L2 mutations may predict early tumor recurrence." (PMID 34543520, 2022). "used this model to develop a murine brainstem pHGG tumor using H3K27M and ACVR1-G328V genetic alterations, along with NRAS and shp53 as oncogenic drivers." (PMID 35978801, 2022). "The same group also showed that tumor growth was reduced by single targeting of ERBB2 in cetuximab-resistant, quadruple (i.e., KRAS, NRAS, BRAF, and PIK3CA) wt CRC patient derived xenografts with ERBB2 mutations." (PMID 35582524, 2022). "For the KRAS, NRAS, and BRAF V600E genes, the concordance rates between the tumor tissue test by PCR and ctDNA test by NGS were 86.4%, 86.4%, and 100%, respectively." (PMID 35280779, 2022). "Currently, due to the reduced cost of genetic testing, the genotyping of tumor biomarkers such as BRAF, KRAS, NRAS, and MSI is possible." (PMID 36136880, 2022). "The clinical data demonstrated a strong correlation between up-regulation of NRAS in the mostly luminal DCIS and the emergence of basal-like properties and more aggressive tumor activities, such as higher level of proliferation and invasion." (PMID 36258226, 2022). "Tumor biopsies were examined as wild-type KRAS (exon 2, 3, 4), NRAS (exon 2, 3, 4) and BRAF V600E for all patients included in this study." (PMID 34335943, 2021). "Current guidelines for the therapeutic management of patients with mCRC recommend KRAS, NRAS, BRAF and high microsatellite instability (MSI-H) profiling on tumor tissue samples." (PMID 34943612, 2021). "For these reasons, the KRAS status of liquid biopsy tends to be less reflective in NRAS, BRAF, EGFR, and MSI of the origin tumor." (PMID 34442609, 2021). "Among them, SHC1, FKBP4, NRAS, KRAS had higher expression, and PRKCD, ADCY9 had lower expression in LUAD tumor tissues compared with normal tissue." (PMID 33936178, 2021). "GEO datasets validated that the 6 genes (SHC1, FKBP4, NRAS, PRKCD, KRAS, ADCY9) had different expression between tumor tissues and adjacent normal tissues in LUAD, and 3 genes (FKBP4, KRAS, ADCY9) were related to the prognosis of LUAD." (PMID 33936178, 2021). "In the HPA database, NRAS, STEAP3, and ALOX5 proteins are significantly expressed in tumor tissues, but the difference in the expression of ZFP36 and GABARAPL1 proteins is not obvious." (PMID 34868262, 2021).
tumor (continued). "A biopsy of the original tumor was sent for panel-based genomic testing in 2019 which identified the tumor as KRAS WT, NRAS WT, BRAF WT (Caris, Irving, TX, USA)." (PMID 34504655, 2021). "When adjusted for gender, age, and tumor size, the prognostic effects of KPNA2 (p < 0.001) and NRAS (p < 0.05) also existed, whereas the independent prognostic value of GRB2 was not so significant (p = 0.074, p > 0.05)." (PMID 33193737, 2020). "To better understand the gene signature influencing patient survival, we conducted a subgroup analysis and mainly focused on tumor stage (clinical or AJCC stage) and molecular characteristics (BRAF and NRAS status)." (PMID 32411243, 2020). "SCNVs shared within the tumor-organoid pairs encompassed regions including BC-relevant genes, such as the tumor suppressor genes APC, PTEN, and ARID1; the oncogenes NRAS, and NOTCH1." (PMID 33371412, 2020). "The BRAF, NRAS and NF1 driver alterations all activate the mitogen‐activated protein kinase (MAPK) pathway and generally occur at the earlier stages of tumour evolution." (PMID 30511391, 2019). "Our analysis suggested that let7c-5p-NRAS and miR-125b-5p-E2F2/E2F3 are several tumor suppressive pathways in HBV-related HCC." (PMID 30602391, 2019). "ERK reactivation under MEK inhibition has been reported to be the main problem in therapeutic strategies aimed at NRAS and KRAS mutant tumours, with ERK being the critical node between responsiveness to MEK inhibition and MAPK reactivation." (PMID 31126017, 2019). "BRAF-MAF was found to be in the range of 2.2–80.3%, while NRAS-MAF was in the range of 4.6–71.0%, indicating log range differences between various tumor samples." (PMID 31391014, 2019). "Tumor molecular profiling was retrieved from clinical documentation when available: 62% (n = 44/71) were KRAS mutant, 3% (n = 2/58) NRAS mutant, 4% (n = 3/68) BRAF mutant and 20% (n = 6/30) HER2 amplified." (PMID 31355139, 2019). "Treatment of M93‐047 NRAS‐mutant xenografts with vehicle, BETi (JQ‐1 or OTX‐015), MEKi (PD901), or BETi plus MEKi, demonstrated that BETi/MEKi combinations led to sustained tumor growth inhibition compared to single agents." (PMID 29650805, 2018). "In a recent study, we found that anti-Notch2 treatment can reduce both HCC and ICC tumor load induced by AKT and neuroblastoma RAS viral oncogene homolog (NRas) oncoproteins, whereas Notch1 suppression decrease HCC and augments ICC occurrence." (PMID 29545603, 2018). "The authors analyzed inter- and intra-tumor heterogeneity by means of single cell RNA-seq, identifying CDK4, highly expressed in most of the sub-clones derived from BRAF wt/NRAS wt tumors, as a potential therapeutic target." (PMID 29491834, 2018). "KRAS, NRAS and BRAF are kinases involved in the RAS-RAF-MAPK signaling pathway and also potential tumor-driven genes." (PMID 30416987, 2018). "The clinicopathologic variables compared with FBXW7 status included age, sex, race/ethnicity, site of the primary tumor, histologic grade, and KRAS, NRAS, BRAF, PIK3CA, and microsatellite instability status." (PMID 28424412, 2017). "The reduction of miR-377–3p and let-7e leads to tumor progression through the miR-377–3p/E2F3 and let-7e/NRAS signaling pathway." (PMID 29026116, 2017).
tumor (continued). "Taken together, our results demonstrate that only BRAF is necessary during the early stages of NRAS-induced melanomagenesis, thereby revealing a specific function for BRAF in tumour initiation that cannot be compensated by ARAF and CRAF." (PMID 28497782, 2017). "As we already suggested earlier, a subset of patients (showing gene mutations in PIK3CA, HRAS, KRAS, NRAS and BRAF or ALK translocation) could benefit from a systemic treatment with a PI3K, MEK, BRAF or ALK inhibitor in the case of unresectable or metastasized tumor stage." (PMID 29312620, 2017). "In patients with sequencing data from matched samples, the concordance between the primary tumour and the PM for KRAS, NRAS and BRAF was 93% (14/15), 100% (15/15) and 100% (14/14 patients) respectively." (PMID 29029407, 2017). "Complete RAS data were available for 143 of 150 patients, of whom 69 (45%) had RAS WT tumours (i.e., WT for exons 2, 3 and 4 of both KRAS and NRAS)." (PMID 27764839, 2016). "The dependency of KRAS mutant tumor cell lines upon CDK6 was readily apparent (rho = −0.38), but was stronger when KRAS, HRAS, NRAS, or BRAF mutant tumor cell line models were combined as a group (rho = −0.43)." (PMID 26947069, 2016). "Three tumors (cases 2, 7, 12) presented KRAS12−13 PLLM or MUT in at least one of the tumor areas selected, but they also presented other KRAS or NRAS MUT or PLLM in other areas of the tumor (case 2) or in the same area (case 7, 12)." (PMID 27916952, 2016). "In combination with chemotherapy, these therapies are the only approved biomarker-driven therapies currently licensed for treatment of CRC and have extended survival up to 41.3 months in patients with tumours wild type (WT) for KRAS and NRAS." (PMID 27340376, 2016). "We show that oncogenic NRAS stimulates IFI6 expression to facilitate melanocyte transformation and tumor growth." (PMID 27608486, 2016). "As samples from the AIO KRK-0104 trial were only tested for KRAS exon 2 codon 12/13 mutations, but not for KRAS exon 3, 4 or NRAS mutations, our data might contain a bias of approximately 10 % hidden mutations that we cannot identify due to lacking tumor material." (PMID 24816724, 2014). "From the 116 tumor blocks sampled, 50 produced DNA of sufficient quality for both MLPA and BRAF/NRAS analysis, 25 produced results for MLPA only, 21 produced results for BRAF/NRAS only and 20 did not produce any results." (PMID 20140953, 2010). "Interestingly, NRAS is a target of tumor suppressor miR-515-5p, which is downregulated in GBM biopsies, indicating the oncogenic role of NRAS in this tumor." (PMID 40362343, 2025). "NGS of this tumor specimen was again negative for BRAF, KIT, NF1, and NRAS mutations, but was again notable for a missense mutation in EZH2 (c.2075 C > T, p.A692V)." (PMID 39984702, 2025). "Molecular profiling through next-generation sequencing (NGS) is essential for therapeutic planning; in our patient, the tumor was negative for BRAF, NRAS, and KIT mutations." (PMID 40937205, 2025). "An EGFR inhibitor is added if the tumor is wild-type for KRAS, NRAS, and BRAF." (PMID 40004690, 2025). "CD24+CD271+ staining is therefore not specific to tumours that are BRAF/NRAS wildtype, nor to BRAF/NRAS mutant tumours." (PMID 40754577, 2025).